RAI1 (retinoic acid induced 1)
Description:
Transcriptional regulator of the circadian clock components: CLOCK, BMAL1, BMAL2, PER1/3, CRY1/2, NR1D1/2 and RORA/C. Positively regulates the transcriptional activity of CLOCK a core component of the circadian clock. Regulates transcription through chromatin remodeling by interacting with other proteins in chromatin as well as proteins in the basic transcriptional machinery. May be important for embryonic and postnatal development. May be involved in neuronal differentiation.
Synonyms: KIAA1820; DKFZP434A139; SMS; MGC12824; SMCR
Tractability: PROTAC: UniProt records ubiquitination sites on it; ubiquitination databases record sites on it; its protein half-life has been measured.
Gene: Protein-coding gene on chromosome 17 (17,681,458 to 17,811,453, forward strand). Ensembl gene ENSG00000108557.
Subcellular location: Cytoplasm; Nucleus
Subcellular location (Human Protein Atlas): Nucleoplasm
Pathways (Reactome):
Cellular responses to stimuli: Heme signaling
Circadian clock: Expression of BMAL (ARNTL), CLOCK, and NPAS2
Gene Ontology:
Molecular function: protein binding; transcription coregulator activity
Biological process: circadian regulation of gene expression; positive regulation of DNA-templated transcription; regulation of transcription by RNA polymerase II
Cellular component: nucleoplasm; nucleus; cytoplasm
Genetic constraint (gnomAD): Loss-of-function variants: 9 observed, 122.16 expected, observed/expected ratio (o/e) 0.0737, 90% interval 0.043 to 0.13. The upper end of that interval is the gene's LOEUF score, 0.13, which puts it in group 1 of 6, group 1 being the genes least tolerant of losing a copy. Missense variants: 2,247 observed, 2,585.3 expected, observed/expected ratio (o/e) 0.87, 90% interval 0.84 to 0.9. Synonymous variants: 1,226 observed, 1,148.7 expected, observed/expected ratio (o/e) 1.07, 90% interval 1.02 to 1.12.
Gene-disease validity (ClinGen):
ClinGen rates the evidence that RAI1 causes each of these diseases.
Smith-Magenis syndrome (autosomal dominant): Definitive. Smith-Magenis syndrome (SMS) is a complex genetic disorder characterized by variable intellectual deficit, sleep disturbance, craniofacial and skeletal anomalies, psychiatric disorders, and speech and motor delay.
Homologues: Orthologues: chimpanzee RAI1 (99% identical), macaque RAI1 (97% identical), dog RAI1 (90% identical), pig RAI1 (83% identical), rat Rai1 (83% identical), mouse Rai1 (82% identical), guinea pig RAI1 (70% identical), tropical clawed frog rai1 (43% identical), zebrafish rai1 (25% identical), Drosophila melanogaster CG5098 (12% identical). Paralogues in human: TCF20 (24% identical).
Diseases named in the same sentence as RAI1 in open-access papers:
RAI1 is named in the same sentence as 90 diseases in open-access papers, as found by Europe PMC text mining. Sharing a sentence is not in itself a finding about the gene and the disease. The quoted sentences say what the papers report.
Smith-Magenis syndrome (47 papers, 2009 to 2026). "A CRISPR-based approach was then used for gene editing in vivo and in vitro, targeting Retinoic acid-induced 1 (Rai1), the causal gene for Smith-Magenis Syndrome, a neurodevelopmental disorder." (PMID 38956550, 2024). "Our work provides evidence that rAAV-CRISPRa therapy during early adolescence can boost the expression of healthy Rai1 allele and modify disease progression in a mouse model of Smith-Magenis syndrome." (PMID 36410433, 2022). "Haploinsufficiency in retinoic acid induced 1 (RAI1) causes Smith-Magenis syndrome (SMS), a severe neurodevelopmental disorder characterized by neurocognitive deficits and obesity." (PMID 36410433, 2022). "Smith-Magenis syndrome (SMS) is a neurobehavioral disorder caused by haploinsufficiency of the retinoic acid-induced 1 (RAI1) gene on chromosome 17p11.2." (PMID 34576033, 2021). "A heterozygous deletion at chromosome 17p11.2 region that includes RAI1 (or a heterozygous intragenic RAI1 pathogenic variant) characterizes the Smith-Magenis syndrome." (PMID 32092880, 2020). "A recent study by Liu and colleagues identified mutations in TCF20, a paralog of RAI1, among individuals manifesting a novel syndrome that has phenotypes similar to those of Smith-Magenis syndrome (a disorder caused by disruption of RAI1)." (PMID 31014384, 2019). "The Smith-Magenis syndrome is caused by disrupted function of RAI1, the gene with the highest XP-CLR score in our study." (PMID 29950181, 2018). "Currently, interest in study of RAI1 gene has rapidly increased due to its association not only with Smith-Magenis syndrome but also with some other neurodegenerative and neuropsychiatric disorders." (PMID 27082237, 2016). "Here, we present a case of a six year old female with a newly identified maternally inherited copy number loss that lies within the Smith-Magenis syndrome common deletion region, but RAI1 copy number is normal." (PMID 26442755, 2015). "Copy number loss of RAI1 results in Smith-Magenis syndrome while copy number gain results in Potocki-Lupski syndrome." (PMID 26442755, 2015). "Smith-Magenis Syndrome (SMS) is a complex genomic disorder mostly caused by the haploinsufficiency of the Retinoic Acid Induced 1 gene (RAI1), located in the chromosomal region 17p11.2." (PMID 23028815, 2012). "There are only rare cases with patients with Smith-Magenis Syndrome associated with heterozygous missense mutations in the RAI1 coding region." (PMID 20738874, 2010). "In addition, the closest established episignatures resembling NOTCH1 were found to be KMT2D-related as well as Smith-Magenis syndrome, which is associated with impairment of RAI1." (PMID 41501857, 2026). "A chromosomal deletion of RAI1 in mice is associated with a short circadian period, whereas in humans it is associated with the Smith-Magenis syndrome, a pathology that is characterized by an inverted melatonin rhythm, sleep disturbances, abnormal feeding, and cognitive disturbance." (PMID 30449276, 2018). "Additionally, the RAI1 gene is associated not only with Smith-Magenis syndrome but also with some other neurodegenerative and neuropsychiatric disorders." (PMID 27082237, 2016). "It is possible that patient 1 and patient 2 may have a blended phenotype; patient 1 has a paternally inherited missense mutation in RAI1, which is associated with Smith-Magenis syndrome." (PMID 26739615, 2016). "Smith-Magenis syndrome is a rare syndromic condition associated with an interstitial deletion of the short arm of chromosome 17 (17p11.2) containing the retinoic acid-induced 1 (RAI1) gene or due to mutation of RAI1." (PMID 20181043, 2010). "Phenotypic features of Smith-Magenis syndrome patients with a 17p11.2 deletion or RAI1 mutation." (PMID 20932317, 2010). "Smith-Magenis syndrome (SMS) is caused by a variation or deletion to the retinoic acid induced 1 (RAI1) gene on chromosome 17p11.2." (PMID 37810798, 2023).
Smith-Magenis syndrome (continued). "Smith-Magenis syndrome (SMS), linked to Retinoic Acid Induced (RAI1) haploinsufficiency, is a unique model of the inversion of circadian melatonin secretion." (PMID 31330985, 2019). "Deletions and mutations involving the Retinoic Acid Induced 1 (RAI1) gene at 17p11.2 cause Smith-Magenis syndrome (SMS)." (PMID 29794985, 2018). "Smith-Magenis syndrome (SMS) is a rare and complex genetic syndrome caused by an interstitial deletion of chromosome 17p11.2 or a mutation on the retinoic acid induced 1 gene." (PMID 29321841, 2018). "RAI1 (retinoic acid induced-1) is a dosage-sensitive gene that causes Smith-Magenis syndrome (SMS) when mutated or deleted and Potocki-Lupski Syndrome (PTLS) when duplicated, with psychiatric features commonly observed in both syndromes." (PMID 26743651, 2016). "As is well known, Smith-Magenis Syndrome (SMS) is caused by mutations in the RAI1 gene on chromosome 17p11.2 (SMS, OMIM# 1882290)." (PMID 26274329, 2015). "The first targeted gene in this species is the Retinoic acid-induced 1 (Rai1) gene, whose haploinsufficiency is responsible for Smith-Magenis Syndrome (SMS), a neurodevelopmental disorder." (PMID 38956550, 2024). "RAI1 is responsible for the Smith-Magenis syndrome in humans, that as in mice presents with craniofacial and skeletal abnormalities." (PMID 28743860, 2017). "Smith-Magenis Syndrome is a contiguous gene syndrome in which the dosage sensitive gene has been identified: the Retinoic Acid Induced 1 (RAI1)." (PMID 20738874, 2010). "As an example, we show that when MBD5 and RAI1 are both haploinsufficient they share common perturbed pathways that likely contribute to the overlapping phenotypes exhibited by 2q23.1 deletion syndrome and Smith-Magenis syndrome patients." (PMID 25853262, 2015). "Smith-Magenis syndrome (SMS) is a neurodevelopmental disorder caused in a majority of cases from a deletion of a portion of chromosome 17p11.2, which includes the retinoic acid-induced 1 (RAI1) gene, whereas a smaller proportion arises from disruptions affecting the RAI1 gene itself." (PMID 40443456, 2025). "Rai1 haploinsufficiency is responsible for Smith-Magenis Syndrome (SMS), a rare neurodevelopmental disorder characterized by obesity, autistic behavior, and circadian rhythm and sleep disturbances." (PMID 38956550, 2024). "The genetic defect leading to Smith-Magenis syndrome (SMS) is deletion of the RAI1 (retinoic acid-induced 1) gene on 17p11.2." (PMID 34848785, 2021). "Notably, this study is the first report about patients with RAI1 mutations whose HL is not accompanied by specific traits typical for Smith-Magenis syndrome." (PMID 27082237, 2016). "Notably, this is the first reported instance of patients with RAI1 missense mutation whose HL is not accompanied by specific traits typical for Smith-Magenis syndrome." (PMID 27082237, 2016). "In that regard, Smith-Magenis syndrome (SMS) is a formidable approach to better understand circadian melatonin secretion cycle disorders and the role of the Retinoic Acid Induced (RAI1) gene in this cycle." (PMID 31330985, 2019). "Retinoic acid induced 1 (RAI1), located in an unstable region on chromosome 17p11.2, is involved in Smith-Magenis syndrome (MIM182290), a disorder with cognitive impairment and behavioral abnormalities." (PMID 19492091, 2009). "Also interesting is the possibility of overlap with Smith Magenis syndrome, in cases where the PMP22 deletion also includes the RAI1 gene." (PMID 41300731, 2025). "These deletions partially overlap the region involved in Smith-Magenis syndrome (SMS); however, the phenotype of the patient and mother is not similar to that of SMS, and the deletion does not affect the retinoic acid induced 1 (RAI1) gene, thought to cause most of the SMS core phenotype." (PMID 31277718, 2019).
Smith-Magenis syndrome (continued). "Retinoic acid induced 1 (RAI1) transcriptionally regulates CLOCK, and haploinsufficiency of RAI1 is the primary contributor to the Smith-Magenis syndrome phenotype, a disorder characterized by circadian rhythm and sleep disruption, intellectual disability, and obesity." (PMID 27763782, 2016). "A recent study described a novel nonsense mutation in the Smith-Magenis gene, RAI1, in a patient previously diagnosed with ROHHAD (though the authors note that deeper evaluation revealed his phenotype was not consistent with ROHHAD or Smith-Magenis syndrome)." (PMID 26302956, 2015). "It is worth mentioning that there is a very similar syndrome, but without BDE, known as Smith-Magenis syndrome (SMS; OMIM#182290) which is caused by deletions in 17p11.2 or mutations in the RAI1 gene." (PMID 24028571, 2013).
Obesity (26 papers, 2011 to 2025). Accumulation of substantial excess body fat. "In patients with RAI1 variants (16%, n = 3/24), obesity was more prevalent than those with 17p11.2 deletion (100% vs 38%)." (PMID 39162735, 2024). "In line with our data, obesity was previously found in 12.9% of individuals with 17p11.2 deletion and in 66.7% of patients with RAI1 variants." (PMID 39162735, 2024). "The molecular involvement of RAI1 gene in metabolic homeostasis and how its pathogenetic variants predispose to obesity still need to be defined clearly." (PMID 39162735, 2024). "Patients with RAI1 variants are more likely to exhibit characteristic behavioral patterns and severe obesity." (PMID 39162735, 2024). "Our data confirm that obesity had a higher prevalence in patients with RAI1 variants (n = 3, 16%) than those with 17p11.2 deletion (100% vs 38%)." (PMID 39162735, 2024). "These deficits manifest in hyperphagia and obesity in Rai1-deficient mouse models, recapitulating the metabolic disturbances observed in patients with SMS." (PMID 39766920, 2024). "Selective Rai1 loss from all BDNF-producing cells or from BDNF-producing neurons in the paraventricular nucleus of the hypothalamus (PVH) induced obesity in mice." (PMID 37956053, 2023). "We identified a novel heterozygous variant of the retinoic acid induced 1 gene (RAI1), c.785G>A p.R262Q, in a 4-year-old Egyptian boy with obesity, hyperphagia, inattentiveness, hyperactivity, and developmental delay." (PMID 37329217, 2023). "In SMS mice, we show that PVH-specific rAAV-CRISPRa gene therapy enhances the expression of the remaining wildtype (WT) Rai1 allele, fully reverses repetitive behavior and partially rescues hyperphagic obesity and delays its onset." (PMID 36410433, 2022). "Our previous cell type–specific study found that Rai1 loss from Vglut2Cre-lineage subcortical excitatory neurons (but not Emx1Cre -lineage cortical excitatory neurons) recapitulates SMS-like obesity and neurobehavioral features in mice." (PMID 36410433, 2022). "The accumulation of TGs is consistent with the fact that RAI1 haploinsufficiency is strongly associated with a tendency toward obesity in SMS patients." (PMID 36411275, 2022). "Supporting the fact that RAI1 is involved in the obesity phenotype, Bdnf, a gene associated with obesity and hyperphagia, was found downregulated in the hypothalamus of the mouse model for Rai1 haploinsufficiency." (PMID 25411582, 2014). "In evaluating the clinical features of SMS in relation to molecular results, we found that a high BMI and obesity are characteristic of the de novo RAI1 variant cases (4/5), as previously reported (6/9 or 67%)." (PMID 21857958, 2011). "This study suggested that Rai1-haploinsufficient mice were more susceptible to diet induced obesity, and a high fat or high carbohydrate diet might trigger early onset obesity in SMS patients." (PMID 39162735, 2024). "Importantly, loss of Rai1 in GABAergic or subcortical excitatory neurons reduced learning ability in fear conditioning, while Rai1 loss in the subcortical excitatory neurons Sim1+ or SF1+ cells caused obesity." (PMID 39766920, 2024). "In particular, our analysis highlights that SMS ‘deleted’ patients may show a dyslipidemic pattern, while ‘mutated’ patients carrying RAI1 variants are more likely to develop early-onset obesity along with hyperinsulinemic dysregulation." (PMID 37761412, 2023). "SMS (Rai1+/-) mice exhibit obesity associated with hyperphagia and increased adiposity." (PMID 37956053, 2023). "The most widely accepted hypothesis is that RAI1 haploinsufficiency causes compulsive hyperphagic behavior, which is the main cause of obesity in patients, and this aspect has been replicated in animal models of disease." (PMID 36411275, 2022).
Obesity (continued). "Among RAI1 target genes are Bdnf (brain-derived neurotrophic factor) and Htr2c (serotonin receptor 2c), both of which are implicated in hyperphagia leading to obesity, a phenotype accompanying SMS, concomitant with altered locomotor activity." (PMID 28548639, 2017). "Haploinsufficiency of the RAI1 gene is associated with Smith–Magenis syndrome, a rare disorder that includes craniofacial, behavioural and neurological signs including intellectual difficulties and sleep disturbance, as well as obesity." (PMID 24519454, 2015). "In order to determine if these mixed background Rai1+/− mice expressed any obesity associated comorbidities, and it is well established that truncal adipose tissue has a significant impact on the development of insulin resistance, we assessed fasting glucose levels." (PMID 25127133, 2014). "Obesity has been reported in >50% of SMS patients with either deletion or mutation of the RAI1." (PMID 25411582, 2014). "However, patients with RAI1 mutations exhibit a higher prevalence of sleep disturbances, aggressive behaviour, compulsive behaviour/motor stereotypes, autistic traits, overeating and overweight/obesity compared with those with 17p11.2 deletions." (PMID 40437981, 2025). "Reduced PVHBDNF neuronal activity upon Rai1 loss could potentially explain obesity, consistent with a previous report that found chemogenetic activation of PVHBDNF neurons promotes negative energy balance by decreasing feeding and increasing energy expenditure." (PMID 37956053, 2023). "Finally, we also know that SMS patients with RAI1 variants may have a higher propensity to obesity, but our results indicate a risk of developing higher insulin concentrations in mutated SMS patients than in those with a deletion of the 17p11.2 region." (PMID 37761412, 2023). "RAI1 deficiency in Sim1+ cells, which include Vglut2+ PVH neurons, is a major contributor to overeating and obesity observed in NestinCre, RAI1CKO mice." (PMID 40724914, 2025). "Early interventions targeting RAI1, particularly before adolescence, hold promise for mitigating SMS-related obesity and associated behavioural phenotypes (Refs 13, 59, 58)." (PMID 40437981, 2025). "Although the obesity and some behavioral traits have been recapitulated in Rai1-knockout mice, Rai1+/− mice “clearly differ from SMS patients” regarding their sleep and circadian rhythms." (PMID 38956550, 2024). "Our work indicates that PVHBDNF neurons depend on RAI1 to maintain normal neuronal activity and regulate body weight homeostasis, and dysfunction of BDNF downstream signalling contributes to obesity associated with SMS mice." (PMID 37956053, 2023). "What additional RAI1-dependent hypothalamic cell types residing in brain regions other than PVH regulate obesity in SMS?" (PMID 37956053, 2023). "Using a homozygous Rai1 conditional knockout (Rai1-cKO) mice, we found that Rai1 deletion in either subcortical excitatory neurons (vGlut2+) or single-minded homolog 1 (Sim1+) neurons induced obesity in mice." (PMID 37956053, 2023). "Retinoic acid-induced 1 (RAI1) haploinsufficiency causes Smith–Magenis syndrome (SMS), a genetic disorder with symptoms including hyperphagia, hyperlipidemia, severe obesity, and autism phenotypes." (PMID 37956053, 2023). "More recently, we found that PVH-specific overexpression of brain-derived neurotrophic factor (Bdnf), one of Rai1’s direct target genes, during early adolescence was sufficient to fully rescue obesity in SMS mice." (PMID 36410433, 2022). "Here we show that PVH-specific Rai1 activation delays the onset of obesity and partially rescues excessive weight gain and food intake." (PMID 36410433, 2022). "We previously show that postnatal Rai1 deletion from PVH was sufficient to induce SMS-like obesity, suggesting that Rai1 expression in the postnatal brain mediates food intake." (PMID 36410433, 2022).